SOAT1 (sterol O-acyltransferase 1)
Diseases named in the same sentence as SOAT1 in open-access papers (continued):
Sharing a sentence is not in itself a finding about the gene and the disease.
prostate carcinoma (124 papers, 2008 to 2026). A carcinoma that arises from epithelial cells of the prostate gland. "Other groups also reported that SOAT1 is upregulated in prostate cancer tissues and is associated with earlier recurrence, and genetic inhibition of SOAT1 leads to the suppression of tumor growth in mice." (PMID 36009491, 2022). "Mounting evidence has indicated that high SOAT1 expression is accompanied by high CE content in glioblastoma, pancreatic cancer, prostate cancer, and other tumors." (PMID 37980334, 2023). "The over-expression of SOAT1 has been recognized as an indicator of tumor progression in glioblastoma, pancreatic cancer, and prostate cancer.The high expression of SOAT1 was positively correlated with poor prognosis of HCC patients." (PMID 38071335, 2023). "Sterol O-acyltransferase 1 (SOAT1) is known to contribute to the growths of liver cancer, pancreatic cancer, and prostate cancer through promoting cholesterol ester synthesis." (PMID 34914638, 2022). "The GEPIA database and GSEA suggest that the SOAT1 protein is highly expressed in prostate cancer samples." (PMID 34461908, 2021). "Similarly, in prostate cancer, SOAT1 inhibition by avasimibe suppresses tumor proliferation and metastasis via the E2F-1 signaling pathway." (PMID 40707931, 2025). "Notably, several studies have reported high SOAT1 expression in prostate cancer, pancreatic cancer, malignant glioma, and some other tumors, accompanied by high cholesteryl esters content." (PMID 33637695, 2021). "In malignant glioma and prostate cancer, avasimibe-mediated SOAT1 inhibition could elevate intracellular cholesterol content, consequently impeding SREBP1 activity and SREBP1-modulated fatty acids synthesis and uptake." (PMID 33637695, 2021). "Both SOAT1 and SOAT2 staining was localized to the cytoplasmic region of prostate cancer cells consistent with their known localization at the endoplasmic reticulum." (PMID 34326474, 2022). "Avasimibe, a potent small molecule inhibitor of SOAT1, has been proven to exert anticancer effects against many tumors, including glioblastoma (GBM), hepatocellular carcinoma (HCC) and prostate cancer (PCa)." (PMID 34790132, 2021). "In recent years, mounting evidence has indicated that high expression of sterol O-acyltransferase 1 (SOAT1) is accompanied by high CE content in glioblastoma, pancreatic cancer, prostate cancer, and some other tumors." (PMID 34201030, 2021). "Protein expression of SOAT1 and SOAT2 has not been examined in prostate cancer tissue." (PMID 34326474, 2022).
leukemia (115 papers, 2010 to 2026). A malignant (clonal) hematologic disorder, involving hematopoietic stem cells and characterized by the presence of primitive or atypical myeloid or lymphoid cells in the bone marrow and the blood. "In fact, over-expression of SOAT1 in cancer was seen in multiple analyses across a wide variety of cancer types, including brain, breast, cervical, kidney, head and neck cancer, and leukemia, suggesting a more general role for high SOAT1 expression in cancer." (PMID 34201030, 2021). "The other pathway involves sterol o-acyltransferase 1(SOAT1) in human pancreatic ductal adenocarcinoma (PDAC) cells and NM-6 leukemia cells deficient in solute carrier family 47 member 1 (SLC47A1) to produce fatty acid cholesteryl esters and enhance iron apoptosis sensitivity." (PMID 40855044, 2025).
lung cancer (114 papers, 2012 to 2025). A malignant neoplasm involving the lung. "They found that SOAT1 was highly expressed in human lung cancer cells and that it can promote the invasion of lung cancer cells." (PMID 37304239, 2023). "Furthermore, the SOAT1 protein can activate the PI3K/AKT signaling pathway to promote lung cancer invasiveness by downregulating intracellular free cholesterol levels." (PMID 40223054, 2025). "In statin-sensitive lung cancer cells, atorvastatin reduces intracellular cholesterol esters and downregulates SOAT1 expression, whereas resistant cells maintain both, suggesting that effective statin action requires SOAT1 suppression." (PMID 40707931, 2025).
pancreatic cancer (105 papers, 2013 to 2025). "For example, SOAT1 has been linked to the development of stomach cancer, and pancreatic cancer; HCG11 may influence the development of nasopharyngeal carcinoma; the PAQR6 gene has also been associated with several cancers." (PMID 37020999, 2023). "Cholesterol plays a role as the negative regulator for SREBP2 and the mevalonate pathway, but SOAT1-mediated conversion of cholesterol into CEs abrogates the cholesterol feedback mechanism that promotes mevalonate pathway dependency in pancreatic cancer." (PMID 37958351, 2023). "Patients with SOAT1 expression in pancreatic cancer (evaluated by immunohistochemistry) survived significantly shorter than patients without SOAT1 expression." (PMID 37958351, 2023). "Inhibition of cholesterol esterification by treatment with the SOAT1 inhibitor avasimibe reduces pancreatic cancer cell proliferation in vitro and in vivo, mechanistically suggesting that avasimibe enhances ER stress and apoptosis in pancreatic cancer cells." (PMID 37958351, 2023). "SOAT1 is widely expressed across various cancers, such as breast cancer, renal cancer, liver cancer, glioma cancer, pancreatic cancer and adrenocortical cancer." (PMID 37409263, 2023). "By using an SOAT1 inhibitor or shRNA knockdown, abrogated cholesterol esterification significantly suppressed tumor growth and metastasis in an orthotopic pancreatic cancer mouse model." (PMID 32194787, 2020). "In recent years, many studies have found that tumors such as glioblastoma and pancreatic cancer exhibit high expression of SOAT1 accompanied by high cholesteryl esters, indicating that SOAT1 is also crucial for cancer cells to regulate cholesterol metabolic homeostasis." (PMID 37409263, 2023). "Recent studies have found that the use of the SOAT1 inhibitor AvasimiBE can inhibit the proliferation and migration of HCC cells, and high levels of SOAT1 expression have previously been shown to be associated with a poor prognosis in prostate and pancreatic cancer." (PMID 36672482, 2023). "Alternatively, the suppression of the lipid flippase solute carrier family 47 member 1 (SLC47A1) enhances ferroptosis by favoring the ACSL4–sterol O-acyltransferase 1 (SOAT1) pathway over the ACSL4–LPCAT3 pathway, leading to the production of PUFA cholesterol esters in pancreatic cancer cells." (PMID 39090114, 2024).
psoriasis (105 papers, 2011 to 2026). An autoimmune condition characterized by red, well-delineated plaques with silvery scales that are usually on the extensor surfaces and scalp. "In the GSE54456 dataset, APOE, CYP27A1, FADS1, and SOAT1 showed lower expression levels in psoriasis compared to the control group." (PMID 38273053, 2024). "In GSE66511 dataset, APOE, CYP27A1, FADS1, and SOAT1 were also significantly downregulated in psoriasis." (PMID 38273053, 2024). "Four hub genes APOE, CYP27A1, FADS1 and SOAT1 were downregulated in psoriasis, while were upregulated in leprosy." (PMID 38273053, 2024). "Among DEGs, APOE, CYP27A1, and SOAT1 confirmed as critical mutually exclusive genes, exhibiting opposite expression patterns in psoriasis and leprosy." (PMID 38273053, 2024). "Box plots showed APOE, CYP27A1, and SOAT1 was upregulated in leprosy tissues, whereas their expression was downregulated in psoriasis tissues." (PMID 38273053, 2024). "Correlation analysis between APOE, CYP27A1, SOAT1, and immune cells revealed positive associations between the expression levels of APOE and CYP27A1 and the abundance of six immune cell types in both psoriasis and leprosy patients." (PMID 38273053, 2024). "Chronic inflammation, as present in psoriasis, may alter SOAT-1 and under normolipidemic conditions give rise to CC leading to accelerated atherogenesis under hyperlipidaemic conditions." (PMID 32646751, 2020). "The ROC curves showed that APOE, CYP27A1, and SOAT1 had high AUC percentages in the GSE74481 dataset (reaching 99.2%, 91.5%, and 85.1%, respectively) and low AUC percentages in the psoriasis integrated dataset (reaching 15.0%, 15.0%, and 29.2%, respectively)." (PMID 38273053, 2024).
atherosclerosis (100 papers, 2008 to 2026). A disease characterized by the build-up of fatty material and calcium deposition in the arterial wall resulting in partial or complete occlusion of the arterial lumen. "In mouse models of obesity or atherosclerosis, genetic inactivation of Acat1/Soat1 in the myeloid lineage reduces the inflammatory responses seen in macrophages." (PMID 36982689, 2023). "Previous studies showed that SOAT1 plays a crucial role in the accumulation of foam cells from macrophages, the key pathological process in atherosclerosis." (PMID 37409263, 2023). "In the early time, SOAT1 has been studied extensively as a potential drug target in atherosclerosis and Alzheimer’s disease." (PMID 37409263, 2023). "SOATs, especially SOAT1, have long been studied as a therapeutic target for atherosclerosis and Alzheimer’s disease due to their importance in cholesterol metabolism." (PMID 36009491, 2022). "Previous studies showed the beneficial effects of SOAT1 inhibition in murine disease models, such as atherosclerosis and Alzheimer’s disease." (PMID 36555105, 2022). "The enzyme sterol O-acyltransferases (Soat1 and Soat2), which catalyze the synthesis of CE from free cholesterol, are regarded as a potential target for atherosclerosis and hypercholesterolemia." (PMID 33790973, 2021). "SOAT1 is involved in atherosclerosis, cholesterol content, glucose and lipid metabolism, study have found that overexpression of ACAT1/2 encoded by SOAT1 can significantly inhibit the differentiation of 3T3-L1 preadipocytes." (PMID 34090334, 2021). "SOAT1 is an important protein for regulating cholesterol absorption and it plays a pivotal role in the development of atherosclerosis." (PMID 31684966, 2019). "Overexpression of SOAT1 functions to atherosclerosis and accumulates cholesterol in the gallbladder mucosa." (PMID 21689475, 2011). "However, practical inhibition of SOAT1 or liver-specific inhibition of SOAT1 has been shown to prevent atherosclerosis." (PMID 37949368, 2024). "In addition, in a different mouse model, myeloid Acat1/Soat1 knockout (KO) attenuates pro-inflammatory responses in macrophages and protects against atherosclerosis." (PMID 36982689, 2023). "One of the current challenges for SOAT1 inhibition in the clinic is that most SOAT1 inhibitors were manufactured as candidate drugs to treat atherosclerosis; thus, it is still unknown whether they could cross the blood–brain barrier (BBB)." (PMID 36009491, 2022). "In summary, neither common nor rare variants in SOAT1/2 are associated with lipoprotein levels, atherosclerosis, or Alzheimer’s disease, despite abundant biochemical and mouse studies showing effects on related phenotypes." (PMID 34436484, 2021). "It was indicated in our study that hypermethylation of SOAT1 may promote gene expression and results in atherosclerosis." (PMID 31684966, 2019). "In Soat1 knockout animals, ACAT1 deficiency led to a marked alteration in cholesterol metabolism resulting in massive accumulation of UC, which caused numerous skin and brain lesions, and worsened atherosclerosis." (PMID 24695360, 2014). "In addition, genes Soat1 and Soat2 are known to encode ACAT1 and ACAT2 enzymes in catalyzing the formation of cholesteryl esters, an important process during atherosclerosis formation." (PMID 19835623, 2009). "SOAT1 is expressed in most cells, and although global inhibition of SOAT1 decreases blood cholesterol levels, it does not rescue atherosclerosis." (PMID 37949368, 2024). "SOAT1 inhibitor avasimibe was originally used to treat atherosclerosis, but failed due to the lack of effectiveness in reducing plaque size in phase III clinical trials." (PMID 34201030, 2021). "Studies with more specific inhibitors of Soat1 activity have also shown aggravation rather than alleviation of atherosclerosis in rabbits and mice." (PMID 22022387, 2011).
hepatocellular carcinoma (97 papers, 2005 to 2025). A malignant tumor that arises from hepatocytes. "SOAT1 is also newly identified as a cholesterol metabolism regulator in aggressive hepatocellular carcinoma subtypes, which maintains membrane cholesterol levels to support CSC proliferation and migration." (PMID 41346572, 2025). "In studies of hepatocellular carcinoma, the knockdown of SOAT1 was observed to alter the intracellular distribution pattern of cholesterol and exert an effective inhibitory effect on the growth and migration of hepatocellular carcinoma cells." (PMID 38993570, 2024). "Taken together, our data suggest a proviral role for DGAT1 and SOAT1 in ZIKV infection in hepatoma cells." (PMID 39237833, 2024). "The expression of most cholesterol metabolism related genes in HCC is increased (e.g., HMG-CoA, SQLE, SREBP2, SOAT1), its over-expression promotes proliferation, migration and invasion of hepatoma cells." (PMID 38071335, 2023). "SOAT1 affects the growth and migration of hepatocellular carcinoma cells by promoting the synthesis of cholesterol and consequently." (PMID 37829187, 2023). "In hepatocellular carcinoma, SOAT1 is highly expressed in tumor tissues, and inhibition of SOAT1 by Avasimibe significantly inhibits tumor growth in vivo." (PMID 36009491, 2022). "Of note, high SOAT1 protein expression has already been demonstrated to correlate with a worse prognosis in hepatocellular carcinoma and adrenocortical carcinoma." (PMID 34326474, 2022). "In our previous study, we have also demonstrated that knockdown of the SOAT1 gene can significantly inhibit the growth of hepatocellular carcinoma cell lines." (PMID 35941608, 2022). "The downregulation of SOAT1 has been found to suppress the proliferation and migration of hepatocellular carcinoma cells by reducing the cholesterol content of the plasma membrane, and then inhibiting the integrin and TGF-β signaling pathways." (PMID 35646697, 2022). "Additionally, in hepatocellular carcinoma, SOAT1 promotes epithelial-mesenchymal transition (EMT) and contributes to tumor progression by increasing cholesterol esterification." (PMID 40707931, 2025). "Typically, high expression of SOAT1 is a specific signature of hepatocellular carcinoma (HCC), which can regulate the distribution of cellular cholesterol and promote HCC cell proliferation." (PMID 37409263, 2023). "In recent years, a wealth of studies has revealed that SOAT1 is highly expressed in numerous tumors, among them, pancreatic carcinoma, hepatocellular carcinoma (HCC), and prostatic cancer." (PMID 33637695, 2021). "The SOAT1 protein catalyzes the synthesis of fatty acid-cholesterol esters and promotes epithelial-mesenchymal transition (EMT) in hepatocellular carcinoma by regulating cholesterol metabolism." (PMID 40223054, 2025). "We identified sterol O-acyltransferase 1 (SOAT1) as a promising target for the discovery and development of drugs against hepatocellular carcinoma." (PMID 37594310, 2023). "A proteomics analysis found that high expression of SOAT1 was a signature specific to the S‐III subtype, which alters the distribution of cellular cholesterol, and suppresses the proliferation and migration of hepatocellular carcinoma effectively." (PMID 40135589, 2025). "Downregulation of DGAT1 and SOAT1 compromises ZIKV infection in hepatoma cells but only SOAT1 and not DGAT inhibitor treatment reduces ZIKV infection." (PMID 39237833, 2024). "Thus, SOAT2 might partially compensate the lack of SOAT1 activity in Huh7 cells, explaining the lesser effects on ZIKV replication in hepatoma cells compared to Hmc3 and 1321N1 cells." (PMID 39237833, 2024).
colorectal cancer (95 papers, 2011 to 2026). A primary or metastatic malignant neoplasm that affects the colon or rectum. "In our findings, DFS analyses demonstrated consistent associations between elevated expression of cholesterol synthesis markers, SREBP‐1, SQLE, and SOAT1, and poorer outcomes, particularly in breast and colorectal cancers." (PMID 40707931, 2025). "High intratumor SOAT1 expression also positively correlated to lymph node metastasis and indicated poor patient disease‐free survival and overall survival in colorectal cancer." (PMID 40135589, 2025). "Furthermore, β-catenin can directly bind to SOAT1 promoter element, promoting SOAT1 transcription in colorectal cancer." (PMID 35646697, 2022).
gastric cancer (88 papers, 2012 to 2025). A primary or metastatic malignant neoplasm involving the stomach. "In this study, we identified SOAT1 as a critical biomarker of gastric cancer, it was markedly upregulated in gastric cancer tissues, which was significantly associated with the clinicopathological characteristics and prognosis of gastric cancer patients." (PMID 34790132, 2021). "Sterol O-acyltransferase 1 (SOAT1) has been identified as a promoter of lymph node metastasis in gastric cancer through the activation of the SREBP pathway." (PMID 38440405, 2024). "Collectively, these results indicating that blocking SREBP1 and SREBP2 pathway inhibits SOAT1-mediated lymphangiogenesis in gastric cancer." (PMID 34790132, 2021). "Meanwhile, SOAT1 can promote gastric cancer lymph node metastasis via regulating lipid synthesis." (PMID 37409263, 2023). "In conclusion, our results indicated that SOAT1 promotes gastric cancer lymph node metastasis through lipid synthesis, which suggested that it may be a promising prognostic biomarker for guiding clinical management and treatment decisions." (PMID 34790132, 2021). "In gastric cancer, expression of SREBP2 and cholesterol synthesis are promoted by sterol O-acyltransferase 1 (SOAT1), which facilitates cancer cells lymph node metastasis." (PMID 40308757, 2025). "SOAT1 also induces the expression of SREBP1 and SREBP2, which further enhance the level of VEGFC and ultimately contribute to invasion in gastric cancer." (PMID 37304239, 2023). "In gastric cancer (GC), overexpression of SOAT1 could promote cholesterol ester synthesis and GC cell proliferation." (PMID 37409263, 2023). "Furthermore, SOAT1 induced SREBP1 and SREBP2 expression participated in the pro-lymphangiogenic process via promoting VEGFC expression and ultimately contributed to gastric cancer lymphangiogenesis." (PMID 34790132, 2021).
Obesity (78 papers, 2010 to 2026). Accumulation of substantial excess body fat. "We have previously reported that in a mouse model, A1B reduces inflammatory responses in adipose tissue macrophages and protects against diet-induced obesity by genetic inactivation of Acat1/Soat1 in the myeloid." (PMID 36982689, 2023).
diabetes (70 papers, 2004 to 2026). "After adjustment of male, age, smoking, drinking, hypertension, diabetes, TG, TC, HDL-C and LDL-C, SOAT1 methylation levels were still associated with CHD (P = 0.001, OR = 0.290, 95% CI: 0.150–0.561)." (PMID 31684966, 2019).